RPS6P3 (ribosomal protein S6 pseudogene 3)
Synonyms: RPS6_1_251
Gene: Processed pseudogene on chromosome 2 (101,509,530 to 101,510,222, reverse strand). Ensembl gene ENSG00000237549.
Diseases named in the same sentence as RPS6P3 in open-access papers:
RPS6P3 is named in the same sentence as 2 diseases in open-access papers, as found by Europe PMC text mining. Sharing a sentence is not in itself a finding about the gene and the disease. The quoted sentences say what the papers report.
viral infection (1 paper, 2024). "Collectively, these data demonstrate that lnc-RPS6P3 as a pseudogene-derived lncRNA is induced by viral infection and the IFN signaling pathway and binds to the viral proteins NP and NS1." (PMID 38674599, 2024). "We found that lncRNA lnc-RPS6P3 was up-regulated upon viral infection and poly(I:C) and IFN-β treatment, indicating it was an interferon-stimulated gene." (PMID 38674599, 2024). "Functional analysis demonstrated that overexpression of lnc-RPS6P3 inhibited IAV replication while knockdown of lnc-RPS6P3 promoted viral infection in A549 cells." (PMID 38674599, 2024). "Upon viral infection, lnc-RPS6P3 inhibits oligomerization of NP, leading to a reduction in vRNP activity and interferes the binding of NS1 to RIG-I, leading to increased K63 ubiquitination of RIG-I, which activates the antiviral innate response and inhibits influenza virus replication." (PMID 38674599, 2024).
infection (1 paper, 2024). The state of being infected such as from the introduction of a foreign agent such as serum, vaccine, antigenic substance or organism. "RNA fluorescence in situ hybridization (FISH) confirmed that lnc-RPS6P3 was localized in both the nucleus and cytoplasm and notably induced upon infection with the influenza A virus." (PMID 38674599, 2024). "In this study, we focused on lncRNA RPS6P3 (NONCODE ID: NONHSAT072829), which is upregulated upon infection with the influenza A virus." (PMID 38674599, 2024).